KIF28P (kinesin family member 28, pseudogene)
Description:
Microtubule-dependent motor protein required for mitochondrion morphology and transport of mitochondria in neuronal cells.
Synonyms: KLP-6
Gene: Transcribed unitary pseudogene on chromosome 1 (246,771,837 to 246,839,611, reverse strand). Ensembl gene ENSG00000223519.
Subcellular location: Mitochondrion membrane